Y_RNA (Y RNA )
Gene: Miscellaneous RNA gene on chromosome 11 (33,004,250 to 33,004,345, reverse strand). Ensembl gene ENSG00000200615.
Homologues: Orthologues: chimpanzee Y_RNA (98% identical), macaque Y_RNA (95% identical), guinea pig Y_RNA (82% identical). Paralogues in human: RNY4 (88% identical), RNY4P14 (85% identical), RNY4P6 (85% identical), Y_RNA (85% identical), Y_RNA (84% identical), RNY4P10 (83% identical), RNY4P13 (83% identical), RNY4P3 (83% identical), RNY4P37 (83% identical), Y_RNA (83% identical), RNY4P19 (82% identical), RNY4P23 (82% identical), and 91 more.